FGF23 (fibroblast growth factor 23)
Diseases named in the same sentence as FGF23 in open-access papers (continued):
Sharing a sentence is not in itself a finding about the gene and the disease.
cardiac hypertrophy (continued). "The prevailing view has been that elevated serum phosphate increases CV risk by promoting vascular calcification, and more recently that increased levels of FGF-23 contribute to CV risk by promoting cardiac hypertrophy." (PMID 27448672, 2017). "Due to the early lethality of Fgf23 deficient mice, a direct proof that FGF23 plays an essential role in mediating cardiac hypertrophy is missing." (PMID 28900153, 2017). "An association between FGF23 and cardiac hypertrophy and systolic dysfunction was observed among patients without CKD as well as those with CKD after multivariate adjustment." (PMID 27400031, 2016). "Third, the association between α-Klotho and cardiac hypertrophy or low LVEF was confounded by FGF23, which has a significant relationship with cardiomyopathy." (PMID 27400031, 2016). "It was reported that Klotho-deficient mice develop heart hypertrophy caused by increased circulating Fgf23." (PMID 24797667, 2014). "In addition, we analysed the cardiac expression of different genes that are associated with cardiac hypertrophy including cardiac troponin (Tnnt2), Fgf23 and natriuretic peptide type B (Nppb)." (PMID 39637045, 2024). "Cardiac hypertrophy and fibrosis were linked to increased serum levels of FGF23 in CKD patients." (PMID 35694669, 2022). "Moreover, cardiac hypertrophy is caused by vascular calcification and excess FGF23 secretion related to uncontrolled SHPT and excess PTH induces cachexia." (PMID 36512619, 2022). "FGF23 may mediate some of this risk by promoting cardiac hypertrophy via activation of fibroblast growth factor receptor 4 on cardiomyocytes." (PMID 34359914, 2021). "To date, it is controversially discussed whether high FGF23 causes LVH in healthy individuals or increased FGF23 is just a result of cardiac hypertrophy." (PMID 34778257, 2021). "Decreasing the expression of Klotho may increase fibroblast growth factor 23 (FGF23), and the increased FGF23 level may cause cardiac hypertrophy and CHF." (PMID 33020564, 2020). "Moreover, some experimental data suggest FGF23 as a direct and causal stimulator for cardiac hypertrophy via specific myocardial FGF23-receptor activation, independent from alpha-klotho." (PMID 30013515, 2018). "FGF-23 has a direct effect on cardiac myocytes causing myocardial hypertrophy." (PMID 29850246, 2018). "Here, we test whether elevated FGF23 levels in klotho deficiency invariably leads to cardiac hypertrophy and fibrosis and whether different alterations in mineral metabolism play a role in these effects." (PMID 29977226, 2018). "In addition, multiple CKD-specific risk factors increase the likelihood of cardiac hypertrophy including elevated circulating FGF23 levels and phosphate retention." (PMID 29250031, 2017). "First, owing to the cross-sectional nature of the study, we cannot conclude whether the relationship between FGF23 and cardiac hypertrophy or systolic dysfunction was causal or resultant." (PMID 27400031, 2016). "To this end, we herein investigated whether FGF23 is associated with cardiac hypertrophy and systolic dysfunction by analyzing data from total of 903 patients with various stages of CKD." (PMID 27400031, 2016). "It was also found that association between FGF23 and cardiac hypertrophy might be stronger among patients with CKD stage G1/G2 or CKD stage G3a than among those with CKD stage G3b." (PMID 27400031, 2016). "However, the downside of this putative protection mechanism may be that chronic gain of FGF23 function causes volume expansion, hypertension, and heart hypertrophy through upregulation of distal renal tubular NCC." (PMID 24797667, 2014). "After the stressor (FGF23) is removed, the stress response attenuates leading to a reduction in cardiac hypertrophy." (PMID 39807363, 2025). "Mice lacking the FGF23 gene excreted more sodium in their urine, while mice with high FGF23 levels had increased plasma volume, hypertension, and cardiac hypertrophy." (PMID 41426862, 2025).
cardiac hypertrophy (continued). "Increases in serum FGF23 levels have also been observed following endurance exercise and in pregnancy, which are scenarios of physiologic cardiac hypertrophy as an adaptive response of the heart to increased demand." (PMID 39452290, 2024). "The correlation with LVMI is in agreement with previous studies and increased FGF23 has been reported as a biomarker of myocardial hypertrophy in CKD." (PMID 39433982, 2024). "To study FGF23/FGFR4 in a second model of physiologic cardiac hypertrophy, we analyzed Burmese pythons, which experience up to 40% increase in cardiac mass after ingesting a meal." (PMID 39452290, 2024). "FGF23, which inhibits 1,25(OH)2D synthesis, is reported as a major contributor to myocardial hypertrophy in CKD." (PMID 38722953, 2024). "The effects of locally produced FGF23 include the regulation of inflammation in hepatocytes, the induction of cardiac hypertrophy, or the inhibition of neutrophils." (PMID 38397231, 2024). "Simultaneously, FGF23 acted on cardiac myocytes, inducing pro-hypertrophic genes and promoting cardiac hypertrophy in an autocrine/paracrine manner." (PMID 38846254, 2024). "The induction of cardiac FGF23 and reduced Klotho was strongly linked to LVH in the CKD cohort, with mice displaying more severe cardiac hypertrophy and fibrosis under conditions of higher FGF23 and lower Klotho levels." (PMID 38846254, 2024). "We have previously shown that FGF23 can directly target cardiac myocytes and that elevated serum levels of FGF23 can induce cardiac hypertrophy in animal models of CKD." (PMID 39273260, 2024). "FGF23 has deleterious cardiovascular effects, including cardiac hypertrophy, arterial wall calcification, and alteration of intracellular calcium and smooth muscle cell contractility." (PMID 36828412, 2023). "Further research demonstrated the significance of dysregulated calcium (Ca2+) homeostasis and the interaction with FGF23 signaling in ventricular hypertrophy." (PMID 36831276, 2023). "FGF23, a growth hormone also involved in mediating cardiac hypertrophy, was also expressed at low levels similar to BNP in the hearts of sham and kidney transplanted SNx rats." (PMID 37456824, 2023). "Of note, the high FGF23 levels cause an increase in FGFR4 expression, showing that FGFR4 is responsible for the crucial role of FGF23 in cardiac hypertrophy." (PMID 36831276, 2023). "Fibroblast growth factor-23 is mainly secreted by osteocytes and osteoblasts and can play an important role in angiogenesis, cardiac hypertrophy, fibrosis, and cardiac remodeling." (PMID 37644795, 2023). "Two independent research groups have demonstrated a profound increase in cardiac expression of FGF23 in animal models of myocardial infarction and cardiac hypertrophy." (PMID 36977891, 2023). "It has also been confirmed that activation of local RAAS via the FGF23-mediated process promotes myocardial hypertrophy and fibrosis." (PMID 35974314, 2022). "Intramyocardial and intravenous injection of FGF23 induced cardiac hypertrophy in wild type mice, while FGF receptor blockage was shown to attenuate it in STNx rats." (PMID 35694669, 2022). "Another pathway of FGF23 induced cardiac hypertrophy, which is discussed by the scientific community, is via an induction of sodium and calcium retention, leading to volume expansion and hypertension." (PMID 35559350, 2022). "In a rat model of cardiac hypertrophy by pulmonary artery banding, FGF23 expression was highly upregulated in cardiac myocytes." (PMID 34422725, 2021). "Circulating FGF23 as well as FGF23 secreted by cardiomyocytes interact with a specific receptor FGFR4 to induce myocardial hypertrophy and fibrosis." (PMID 33924991, 2021). "Systemic and myocardial administration of FGF23 in 12-week old C57BL/6 mice induces cardiac hypertrophy." (PMID 33416083, 2021). "Nevertheless, in vivo studies showed that Fgf23 increased sodium uptake in the distal tubule resulting in volume expansion, hypertension and finally cardiac hypertrophy." (PMID 35118076, 2021).
cardiac hypertrophy (continued). "As a potential mechanism of these observations, FGF23 is reported to induce cardiac hypertrophy via Klotho-independent signaling through the FGFR4." (PMID 34765890, 2021). "FGF-23 activates promoting cardiac hypertrophy gene transcription by binding to FGF receptors (FGFRs) on the surface of cardiomyocytes membrane, instead of directly entering the cells." (PMID 34336893, 2021). "FGF23 has a direct impact on the heart that promotes ventricular hypertrophy acting via FGF receptor 4 (FGFR4) in cardiomyocytes." (PMID 34359914, 2021). "Although FGF23 has been reported to induce cardiac hypertrophy, recent studies demonstrated that cardiac hypertrophy and myocardial infarction induce FGF23 production by cardiomyocytes." (PMID 34765890, 2021). "Further studies revealed the importance of calcium (Ca2+) homeostasis dysregulation and the cross-talk to FGF23 signaling in cardiac hypertrophy." (PMID 34065339, 2021). "Recent investigations demonstrated that cardiomyocytes are the source of FGF23 in animal models of myocardial infarction and cardiac hypertrophy induced by transverse aortic constriction or cardiomyocyte-specific activation of calcineurin A." (PMID 34765890, 2021). "Enhanced FGF23 levels are associated with the development of LVH in patients with CKD and it has been shown that FGF23 directly induces cardiac hypertrophy in vitro and in vivo." (PMID 35118076, 2021). "Experimental evidence from other authors and our laboratory has shown that excess FGF23 promotes cardiac remodeling by increasing myocardial hypertrophy and fibrosis." (PMID 33460402, 2021). "Previous studies demonstrated that FGF23 inhibited parathyroid hormone secretion through MAPK pathway or induced myocardial hypertrophy mediated by activation of PLCγ-calcineurin-NFAT pathway." (PMID 33460402, 2021). "It was previously shown that TAC, a model for high blood pressure-induced cardiac hypertrophy and heart failure, induces the expression of cardiac Fgf23 in mice." (PMID 35118076, 2021). "It is important to underline that high FGF23 levels induce upregulation of FGFR4 expression, indicating the induction of cardiac hypertrophy via FGFR4." (PMID 34065339, 2021). "Our findings contrast with previous observations of increased serum FGF23 levels and increased cardiac expression of FGF23 in rodents with myocardial infarction and cardiac hypertrophy." (PMID 34765890, 2021). "Experimentally, FGF23 directly induces cardiac hypertrophy and vice versa cardiac hypertrophy stimulates FGF23." (PMID 35118076, 2021). "In turn, FGF23-mediated activation of local RAAS in the heart promotes cardiac hypertrophy and fibrosis." (PMID 32150864, 2020). "Among these genes, we focused on fibrosis growth factor (FGF) 23 because a previous study had reported that FGF23 plays an important role in cardiac hypertrophy." (PMID 32315372, 2020). "Most of the studies investigating the association of FGF23 and mortality in CKD patients analyzed the presence of cardiac hypertrophy, known to be very common in CKD, and activation of the renin–angiotensin–aldosterone (RAAS) system." (PMID 32106499, 2020). "Compared with wild type mice, the conditional FGF23 knockout in the bone shows higher serum phosphate levels and develops a more severe renal disease and cardiac hypertrophy." (PMID 31698866, 2019). "FGF23 has also been shown to directly promote immune dysfunction, systemic inflammation and cardiac hypertrophy." (PMID 31461904, 2019). "Taken together, besides the established activation of calcineurin/NFAT pathway by FGF23, our data suggest a RAAS-mediated signaling cascade of FGF23-induced cardiac hypertrophy." (PMID 31540546, 2019). "Our data suggest that FGF23-mediated activation of local RAAS in the heart promotes cardiac hypertrophy and fibrosis." (PMID 31540546, 2019).
cardiac hypertrophy (continued). "Most importantly, recent background studies have shown that Klotho protects against cardiac hypertrophy in mice independently of FGF-23, whereas recombinant α-Klotho has been demonstrated to act therapeutically against uremic cardiomyopathy in mice." (PMID 31185930, 2019). "A recent study by Slavic and colleagues investigated cardiac and circulating FGF23 in experimental heart hypertrophy." (PMID 29892269, 2018). "Several studies have shown that repetitive intravenous and intraperitoneal injections of recombinant FGF23 protein in wild-type mice induce cardiac hypertrophy within 5 days, indicating that FGF23 has potent hypertrophic effects on the heart." (PMID 29770125, 2018). "According to the experimental studies, selective blockade of FGF receptor 4 is recommended for treatment of cardiac hypertrophy and fibrosis induced by FGF23 because this process is selectively mediated via FGF receptor 4 activation." (PMID 30200452, 2018). "Among them, serum levels of fibroblast growth factor 23 (FGF23) have been identified, from as early as stage 2 CKD, as one of the earliest biomarkers that start increasing, and correlate with cardiac hypertrophy, heart failure, and all-cause mortality." (PMID 30245879, 2018). "Sixty days after surgeries, VDD+Nx rats exhibited hypertension, a greater decline in renal function and plasma FGF-23 levels, renal hypertrophy, as well as higher plasma levels of PTH and aldosterone." (PMID 30370270, 2018). "Recently, we analyzed myocardial autopsy samples of deceased patients with childhood-onset ESRD and investigated the well-established FGF23/FGFR4 signaling cascade mediating cardiac hypertrophy." (PMID 29892269, 2018). "To obtain further insight into potential FGFR-mediated signalling mechanisms in TAC-induced cardiac hypertrophy, we investigated mRNA expression of Fgfr1, Fgfr3 and Fgfr4 in WT, VDRΔ/Δ, Fgf23−/−/VDRΔ/Δ, and Klotho−/−/VDRΔ/Δ mice, 4 weeks after TAC." (PMID 28900153, 2017). "Using transverse aortic constriction (TAC) in gene-targeted mouse models, we examine the role of Fgf23 and Klotho in cardiac hypertrophy and dysfunction induced by pressure overload." (PMID 28900153, 2017). "Here, we report that FGF23-induced cardiac hypertrophy is reversible in vitro and in vivo upon removal of the hypertrophic stimulus." (PMID 28512310, 2017). "FGF23 appears to be a novel circulating factor that induces cardiac hypertrophy via activating FGFR4 and subsequent calcineurin/NFAT signaling in cardiac myocytes." (PMID 28512310, 2017). "We have previously shown that administration of anti-FGFR4 prevents the development of LVH in the 5/6 nephrectomy rat model of CKD11, indicating that FGF23/FGFR4 is important for the initiation of cardiac hypertrophy in the context of kidney injury." (PMID 28512310, 2017). "They observed that recurrently elevated FGF23 levels via intramyocardial and intravenous injections of FGF23 in mice, led to high rates of ventricular hypertrophy and mortality." (PMID 28974056, 2017). "To determine if FGF23-induced cardiac hypertrophy is reversible in vivo, we elevated serum FGF23 levels in C57Bl/6J mice by administration of a 2% phosphate diet for 3 months, that has been shown to induce LVH11, as well as for 6 months." (PMID 28512310, 2017). "Collectively, the results of the current study provide novel insights into the regulation and the role of Fgf23 in pressure overload-induced cardiac hypertrophy." (PMID 28900153, 2017). "FGF23 is known to produce cardiac hypertrophy by activating calcineurin with concomitant promotion of protein kinase C (PKC), which can increase late sodium current (INa-Late) in the cardiomyocyte." (PMID 27713141, 2016). "Phospholipase Cγ-PKC and phospholipase Cγ-calcineurin pathways has been shown to mediate FGF23-induced ventricular hypertrophy." (PMID 27713141, 2016). "Our group and others have documented that FGF23 can induce cardiac hypertrophy as well as alter calcium handling and contractility." (PMID 27242547, 2016).
cardiac hypertrophy (continued). "Similar to the current study, we previously assessed the possible relationship between FGF23 (or α-Klotho) and cardiac hypertrophy and systolic dysfunction among patients admitted to the cardiology department, although the study population was much smaller." (PMID 27400031, 2016). "Our data showed that chronically elevated circulating levels of intact Fgf23 levels in Hyp mice lead to Na+ retention, hypertension, and heart hypertrophy through increased expression of NCC." (PMID 24797667, 2014). "To further elucidate the pathophysiological role of locally produced FGF23 in LVH, we used mice with a specific deletion of Fgf23 in cardiomyocytes in combination with a well-established model of pressure overload-induced cardiac hypertrophy and failure, transverse aortic constriction (TAC)." (PMID 41152461, 2025). "In the CKD milieu, FGF23 induces cardiac hypertrophy that is accompanied by pathologic alterations, while by itself FGF23/FGFR4 signaling causes hypertrophy that might be beneficial." (PMID 39452290, 2024). "This study raised questions about whether enhanced past cardiac expression of FGF23 mediated pathological cardiac hypertrophy through the stimulation of pro-hypertrophic factors such as endothelin 1 (ET1)." (PMID 38846254, 2024). "To determine whether FGF23/FGFR4 contributes to physiologic cardiac hypertrophy, we studied FGFR4 knockout mice (FGFR4−/−) during late pregnancy." (PMID 39452290, 2024). "In addition to the potential to induce cardiac hypertrophy, experimental data suggest multiple toxic effects of FGF23, including the induction of inflammation, immune dysfunction, and anemia." (PMID 36977891, 2023). "Experimental studies suggested that, in the heart, FGF-23 may contribute to myocardial hypertrophy, endothelial dysfunction and atherosclerosis, and, therefore, may be used as a biomarker of CV disease." (PMID 36676179, 2023). "They suggested that calcium may appear to be a key link between increased FGF23 level, long-term cardiac remodeling, hypertrophy, and finally HF." (PMID 37371618, 2023). "The second is the finding that in most animal models and patients with disorders of primary FGF23 excess, such as X-linked hypophosphatemia, there was no cardiac hypertrophy." (PMID 36977891, 2023). "Moreover, it has been recently described that FGF23-induced cardiac hypertrophy in mice is attenuated by soluble Klotho administration." (PMID 35042527, 2022). "FGF23 is a humoral factor produced by osteocytes and has been recognized as a significant predictor of life prognosis in patients undergoing dialysis, in whom it can induce cardiac hypertrophy, renal anemia, immunodeficiency, and chronic inflammation." (PMID 35710357, 2022). "Fibroblast growth factor 23 (FGF-23), a novel inducer of cardiac hypertrophy and fibrosis through pro-fibrotic gene transcription, is speculated to participate in cardiac remodeling with possible reversibility." (PMID 35622651, 2022). "Interestingly, it has been recently described that FGF-23-induced cardiac hypertrophy is also attenuated by sKL in mice." (PMID 34867481, 2021). "In a previous report, FGF-23–induced cardiac hypertrophy was mediated by the calcineurin pathway." (PMID 33848263, 2021). "PTH-induced cardiomyocyte hypertrophy may be an indirect effect of FGF-23 once high levels of FGF-23 have also been bonded to cardiac hypertrophy and mortality in CKD patients." (PMID 34054588, 2021). "Indeed, experimental data suggest FGF-23 as a direct mediator of cardiac hypertrophy development, cardiac fibrosis and cardiac dysfunction via specific myocardial FGF receptor (FGFR) activation." (PMID 33767635, 2021). "Therefore, the relationship between FGF-23 and cardiac hypertrophy, as well as the former’s direct effect on cardiac remodelling through molecular pathways, has been well established and is discussed in the experimental section (section 3.2)." (PMID 33767635, 2021).